TNF (tumor necrosis factor)
Diseases named in the same sentence as TNF in open-access papers (continued):
Sharing a sentence is not in itself a finding about the gene and the disease.
E. coli infection (continued). "The study suggested that HSPA1B and TNF may be E.-coli-infection-specific genes, which may help explain the molecular mechanism of infectious sepsis." (PMID 38066783, 2023). "Furthermore, E. coli infection resulted in an increase in the mRNA expression of the pro-inflammatory factors TNF-α and IL-1β in the mammary gland, but this increase was attenuated by either Z-d14CFR or gentamicin treatment (p < 0.001)." (PMID 35563007, 2022). "The expression of TLRs in BF of chicks treated with HQD were up-regulated, indicating that HQD regulates the anti-infection ability by increasing the mRNA levels of TLR4, -5 and -15, further decreasing the serum LZM and IL-1β, TNF-α, IL-10, IL-6 level of chicks suffered E. coli infection." (PMID 36198724, 2022). "A similar effect of IL6 has been observed in previous reports, which showed that mice with IL6 deficiency exhibited more severe Escherichia coli infections, and inhibition of IL6 signaling increased the survival of intracellular Brucella abortus in macrophages and decreased the production of TNF–α." (PMID 34439908, 2021). "In brief, the decreased TNF and NF expressions of liver tissues in the agrimos® fed broiler chicks with E. coli infection may be an indication of slowdown inflammation and gradual restoration of the infected broiler chicks’ health status." (PMID 32560684, 2020). "However, the reduction in liver enzyme activities and the down-regulation of NF and TNF gene expressions indicated the protective effects and anti-inflammatory properties of agrimos® in broiler chicks with E. coli infection." (PMID 32560684, 2020). "In agreement, we further found that E. coli infection induced a transient increase (after 1 and 6 h) in brain levels of the pro-inflammatory cytokine tumor necrosis factor α (TNF-α), whereas levels of interleukin 1β (IL-1β) were comparable between groups at the evaluated timepoints." (PMID 30975983, 2019). "Furthermore, the E. coli infection tended to increase the expression of TNF-α and IL-6 (P = 0.057 and P = 0.092, respectively)." (PMID 29948799, 2019). "Moreover, ABPS played a significant role in suppressing the effects of E. coli infection in the CABP group by lowering the concentrations of TNF-α and IL-4 compared to the CNG group." (PMID 30961158, 2018). "All these results suggest that duNLRP3 could induce the mRNA expression of IL-1β, IL-18, and TNF-α during E. coli infection, shows that duNLRP3 plays an important regulatory role in the innate immune response to E. coli." (PMID 30349536, 2018). "In addition, the mRNA expression levels of IL-1β, IL-18, and TNF-α induced by E. coli infection were significantly up-regulated in comparison with the NC-lentiviral vector group (P < 0.01)." (PMID 30349536, 2018). "Abundance of the chemical compound LPS has not been measured, but E. coli infection had increased the mRNA concentrations encoding TNF by 8 fold and IL1B by almost 14 fold." (PMID 28684793, 2017). "In this study, E. coli infection increased the concentration of IL-6 and TNF-α, suggesting that E. coli could induce inflammation in mice through IL-6 and TNF-α production." (PMID 28798800, 2017). "The development of clinical symptoms of CM in the sow was suggested to be associated with a locally increased production of pro-inflammatory cytokines such as interleukin 1-beta (IL1-beta), IL6, IL8, and tumor necrosis factor-alpha (TNF-alpha) in response to intramammary E. coli infection." (PMID 25948480, 2015). "In addition, during natural coliform mastitis or experimental E. coli infection TNF is significantly increased in both milk and serum." (PMID 26705479, 2015). "Furthermore, the levels of IL-1β, IL-6, and TNF-α increase in mammary glands with E. coli infections in mice." (PMID 23626786, 2013). "In addition, significantly lower levels of TNF-α following E. coli infection have been observed." (PMID 40384982, 2025).
E. coli infection (continued). "Consequently, upon E. coli infection of BL-primed A-431 vaginal epithelial cells, the reduction of TNF-α suggests BL may have an immunomodulatory role, but more evidence is needed to directly link this to AV treatment." (PMID 40384982, 2025). "Levels of TNF-α (164 ± 8.3 pg/mL versus 123 ± 3.4 pg/mL, p < 0.001), IL-1β (65 ± 3.3 pg/mL versus 38 ± 2.7 pg/mL, p < 0.001), IL-8 (173 ± 6.3 pg/mL versus 129 ± 8.4 pg/mL, p < 0.001) were found to be augmented in S. aureus infection as compared with E. coli infection." (PMID 36298513, 2022). "At 3 h after E. coli infection, the qPCR results showed that overexpression of mgU2-30 led to a significant increase in the levels of pro-inflammatory cytokines IL-6, TNF-α, and IL-1β, whereas knockout of mgU2-30 did not cause an increase in the level of these cytokines in hBMECs." (PMID 34980188, 2022). "The expression levels of interleukin 1 b (IL1B), IL6, tumor necrosis factor a (TNFA), interleukin-8 (CXCL8), and defensin beta 2 (DEFB2) genes in the endometrium of the GE group were upregulated (p < 0.05) after E. coli infection." (PMID 40075974, 2025). "In differentiating E. coli infection from other bacterial infections, the AUC values of IL2 were 0.5846, HSPA1B was 0.7038, TNF was 0.7116, and the combined value of the three was 0.71." (PMID 38066783, 2023). "In differentiating healthy and E. coli infection groups, the AUC values of IL2 were 0.7299, HSPA1B was 0.7931, TNF was 0.8218, and the combination of the three was 0.8793." (PMID 38066783, 2023). "According to previous studies, pigs with F18+ E. coli infection have increased concentrations of IL6 (60%), IL8 (43%), and TNF-α (28%) in the small intestine of nursery pigs." (PMID 37685055, 2023). "Our results showed that pretreatment with different doses of L. plantarum 17–5 reduced the expression of IL1β, IL6, IL8, TNFα, COX2, iNOS, CXCL2 and CXCL10 during E. coli infection." (PMID 35764986, 2022). "The levels of the inflammatory factors IL-2, IL-6, TNF-α, and MPO were significantly increased after E. coli infection, while MPX reduced the serum levels of IL-6 (p < 0.01), IL-2, TNF-α, and MPO (p < 0.05)." (PMID 34177825, 2021). "A plausible anti-inflammatory effect of EPS was observed in this study, as the expression of the IL12B, TNF, CSF1 and CSF3 genes was abated in the cells pretreated before E. coli infection." (PMID 32234079, 2020). "The results show that IL-1β, IL-18, and TNF-α in the liver, spleen, and brain of the NLRP3-lentiviral vector-injected group mostly increased after E. coli infection." (PMID 30349536, 2018). "It was already shown that TNF-α induces upregulation of EGFR, and in a previous study, we demonstrated that E. coli infection leads to TNF-α release, while PBMO displayed a distinctly increased TNF-α release compared to CBMO." (PMID 30524196, 2018). "In parallel, the mRNA expression of IL-6 and TNF-α was detected in the PLCs collected from the mice infected with E. coli and treated with MS19 once at 1 h after E. coli infection." (PMID 28492513, 2017). "In the present study, E. coli infection activated NF‐κB predominantly through upregulation of TLR4 and accumulation of ROS, rather than through increased I‐κB phosphorylation, leading to elevated production of IL‐6 and TNF‐α." (PMID 41502826, 2026). "Systemic E. coli infection induced substantial increases in IL-6, IFN-γ, TNF-α, and IL-1β." (PMID 41309396, 2025). "E. coli infection significantly induced PGE2 synthesis in BMDMs, which exacerbated the inflammatory response and tissue damage via NF-κB and MAPK signaling pathways, elevating TNF-α, IL-1β, IL-6, and IL-8." (PMID 40666730, 2025). "The results showed that XCHD could significantly reduce the concentrations of IL-1, IL-6 and TNF- α in infected chicks, indicating that XCHD can treat chicken colibacillosis by inhibiting systemic and pulmonary inflammation." (PMID 36678378, 2022).
E. coli infection (continued). "While degranulation may be redundant in the MC response to E. coli, the release of proinflammatory mediators, including tumor necrosis factor (TNF), IL‐8,38, 39, 40 and leukotrienes appear pivotal for E. coli infection recovery." (PMID 32222064, 2020). "In fact, at day 6 following C. jejuni infection, increased IFN-γ, TNF, IL-6 and MCP-1 serum levels could be measured (p<0.001), whereas E. coli infection resulted in elevated IFN-γ and TNF serum concentrations." (PMID 27438014, 2016). "Expression of TNF-α can be induced in a variety of porcine cells, especially in macrophages/monocytes, in response to LPS and other bacterial cellwall products and systemic levels of TNF-α have been observed in response to E. coli infections in pigs." (PMID 18700003, 2008). "Based on our findings, BLP could be contributed to attenuating the proinflammatory cytokine (TNF-α and IL-1β) and chemokine (RANTES) production and enhancing anti-inflammatory cytokine (IL-10) production in mouse sera, lungs, and livers after E. coli infection or LPS stimulation." (PMID 36916913, 2023). "However, compared with uninfected mice group, significant differences in the mRNA expression of IL-10 in jejunum, colon, and spleen and TNF-α in jejunum and spleen were observed in treated MccJ25 mice group after clinically source MDR E. coli strains infection." (PMID 35250983, 2022). "In these studies, E. coli infection increased the concentrations of pro-inflammatory cytokines (IFN-γ, TNF-α, IL-1β, IL-6 and IL-8) and decreased the concentrations of anti-inflammatory cytokine (IL-4), indicating that E. coli could induce inflammation in mice through regulation of cytokines." (PMID 33676495, 2021). "Additionally, in accordance with the previous study which showed that PD effectively inhibited the expression of proinflammatory cytokines including IL-1beta, IL-6, and TNF-alpha, PD treatment also decreased IL-8 and ICAM-1 induced by E. coli infection in our work." (PMID 32714880, 2020). "In contrast to Escherichia coli infections, S. aureus mastitis does not evoke a significant IL-8 or TNF-α response, which might partially explain the chronic nature of S. aureus IMI." (PMID 27176792, 2016). "Although our study demonstrates increased IAP expression following E. coli infection, we did not evaluate TLR4 expression, proinflammatory cytokines (e.g., IL-6 and TNF-α), or NF-κB activation." (PMID 40804973, 2025).
Glucose intolerance (110 papers, 2009 to 2025). Glucose intolerance (GI) can be defined as dysglycemia that comprises both prediabetes and diabetes. "Dysregulation of membrane proteolysis of IR-linked pro-inflammatory Tumor Necrosis Factor Alpha (TNF-α) by TNF-α converting enzyme (TACE)/metalloproteinase 3 (TIMP3) system has been proposed as a common feature of glucose intolerance and vascular inflammation." (PMID 37058160, 2023). "Fecal Bifidobacteria levels were inversely associated with glucose intolerance and inflammatory biomarkers, including IL-1β, IL-6, TNF-α and MCP-1." (PMID 33922965, 2021). "In addition, K6 probiotics significantly mitigated SD-induced weight loss, exercise performance decrement, glucose intolerance, inflammation (TNF-α, IL-1β), tight junction hyperpermeability (Claudin-1, ZO-1), and circadian dysregulation (BMAL-1, CLOCK)." (PMID 40959574, 2025). "Recent studies demonstrated that consumption of farmed salmon containing persistent organic pollutants, including increased levels of seven different PCBs, promoted glucose intolerance associated with elevations in adipose tissue expression of TNF-α in HF-fed mice." (PMID 23099484, 2013). "Thus in an Asian cohort, visceral fat (measured by CT scan) but not subcutaneous fat progressively increased with increasing degree of glucose intolerance and was associated with increased levels of TNF-α." (PMID 23300769, 2012). "Meantime, inflammation can disrupt the insulin signaling pathway and mediate glucose intolerance, with TNF-α further exacerbating metabolic disorders by interfering with the PI3K-Akt signaling pathway." (PMID 40871693, 2025). "In combination with a high-fat diet, B. fragilis not only causes higher metabolic endotoxemia and weight gain, it also increases body fat, total SCFAs, serum Tumor necrosis factor-alpha (TNFα) concentration, and glucose intolerance." (PMID 37503343, 2023). "Continuously elevated levels of IL-6 and TNF-alpha can disrupt carbohydrate metabolism, resulting in glucose intolerance and gestational diabetes mellitus." (PMID 36993820, 2023). "Here, we demonstrated that there the expression of pro-inflammatory cytokines, such as TNF-a, a glucose intolerance factor that links immune cells to metabolic dysfunction, is increased in the wound edge." (PMID 37046252, 2023). "Accordingly, we noted that doxepin treatment led to increases in serum CRP, IL-1β, and TNF-α levels in our doxepin-treated mice, in parallel with glucose intolerance exacerbation." (PMID 33809508, 2021). "Sucrose+HFD showed the highest metabolic endotoxemia, weight gain, body fat, total short chain fatty acids (SCFAs), serum TNFα concentration and glucose intolerance." (PMID 32804018, 2020). "HFD decreased glucose tolerance in C57Bl/6J, whereas TNF-α deletion partially protected from HFD-induced glucose intolerance." (PMID 27562094, 2016). "Our study is the first study to show early signs of glucose intolerance in IUGR rats following elevated TNFα and activation of the UPR." (PMID 24804087, 2014). "By the study done by Yu and his team on 3 month Troglitazone treatment it reversed the inhibitory effect of TNF-α on expression of adiponectin thus reversing glucose intolerance in obese or lean subjects." (PMID 23213322, 2012). "The role of the TNF-α → NF-κB → GLUT4 pathway in POP-induced glucose intolerance was also demonstrated in a study of United States Air Force veterans of the Vietnam War who were involved with spraying the Agent Orange herbicide that was contaminated with TCDD." (PMID 21556177, 2011). "Interestingly, glucose intolerance reduces IL-10 signaling efficiency, resulting in increased TNF-α production." (PMID 37313404, 2023). "This study also showed that consumption of grape polyphenols attenuated several effects of a high-fat diet, including weight gain, glucose intolerance, adiposity, and serum inflammatory markers (interleukin (IL)-6, tumor necrosis factor (TNF)-α, and lipopolysaccharide)." (PMID 35630763, 2022).
Glucose intolerance (continued). "Interestingly, genetically modified mice with reduced TNF-α signaling fed an HFD for 11 weeks showed an increase in glucose intolerance." (PMID 33117273, 2020). "Inflammation can also lead to other pregnancy complications, elevated levels of the pro-inflammatory cytokines Interleukin-6 (IL-6) and Tumour Necrosis Factor—alpha (TNF-α) for example interfere with insulin signalling and lead to glucose intolerance resulting in gestational diabetes mellitus." (PMID 25806806, 2015). "Similarly, a mechanistic understanding of the causative relationships between TNFα and the UPR in the subsequent development of glucose intolerance will also be important." (PMID 24804087, 2014). "We have shown that TNFα mRNA expression was upregulated in the fat tissue, which may play an important role in systemic glucose intolerance in the glucose deposit organs, such as fat itself and skeletal muscle." (PMID 25058584, 2014). "The exact role of the opposite effects and clinical impact of p-TNF-α and p-IL-6 on loss and gain of body weight and indirectly on the development of glucose intolerance is not known." (PMID 20529356, 2010). "Pharmacological inhibition of mTORC1 with rapamycin in HFD-fed mice worsened glucose intolerance and AT inflammation by increasing the number of polarized M1 macrophages, naive and activated cytotoxic T lymphocytes, and proinflammatory markers such as TNF-α, IL-6, and MCP-1." (PMID 28661198, 2018). "Thus, our findings pointing to increased glucose, triglycerides, and glucose intolerance observed in the OB group may be related to decreased adiponectin and increased IL-6, TNF-alpha, and PAI-1." (PMID 28878683, 2017). "Thus, our data suggest that the mechanism linking EFA intake to systemic glucose intolerance may be TNFα- mediated inflammation in adipose tissue." (PMID 27669293, 2016). "PCBs increase tumour necrosis factor-alpha (TNF-α) and interleukin-6 (IL-6), BPA decreases serum adiponectin levels and increases serum IL-6 and TNF-α, leading to IR and glucose intolerance." (PMID 41488239, 2025). "This meta-analysis demonstrated that administration of L-carnitine in diabetic and glucose intolerance patients can significantly reduce TG, LDL-C, FBG, HbA1c, HOMA-IR, CRP, TNF-α, weight, BMI, BFP, and leptin levels." (PMID 39085907, 2024). "Administration of RPE significantly decreased fasting blood glucose, HbA1c, insulin, HOMA-IR, LDL, total cholesterol, triglyceride, plasma IL-β, and plasma TNF-α levels and increased the HDL level as well as improved glucose intolerance." (PMID 35741945, 2022). "Glucose intolerance was partially prevented by L. kefiri treatment (GTT) and local inflammation (TNFα; IL1β; IL6 and INFγ) was completely inhibited in EAT." (PMID 28513533, 2017). "In this study, miR-452 with common target sequence in RETN, TNFα, and CCL2 mRNAs could contribute to worsening glucose intolerance in the IH-condition by up-regulation of RETN, TNFα, and CCL2 mRNAs." (PMID 31013606, 2019). "HFD-fed Sfrp5-deleted mice exhibited accumulation of macrophages (F4/80 and CD68), c-Jun NH2-terminal kinase (JNK) activation, an increase in proinflammatory mediators (TNF-α, IL-6, monocyte chemotactic protein-1 (MCP-1), severe glucose intolerance, and hepatic steatosis." (PMID 28661198, 2018). "While we demonstrated an increase in TNFα components and UPR activation in association with later onset glucose intolerance, we did not assess causative relationships." (PMID 24804087, 2014). "We speculate that programmed dysregulation of TNFα and UPR contributed to the development of glucose intolerance in male IUGR rats." (PMID 24804087, 2014). "Given the important role of TNF in metabolic dysfunction and adipose tissue biology, it is possible that increases in this receptor may compensate for the lack of IL-1 signaling and thereby influence the glucose intolerance observed in male offspring." (PMID 32655404, 2020).
Glucose intolerance (continued). "Although the HFCR treatment did not significantly decrease TNF-α protein levels in adipose tissues, HFCR treatment resulted in the improvement of glucose intolerance." (PMID 22778500, 2012).